BRCA1 (BRCA1 DNA repair associated)
Diseases named in the same sentence as BRCA1 in open-access papers (continued):
Sharing a sentence is not in itself a finding about the gene and the disease.
breast tumors (continued). "However, for common terms such as breast neoplasms, BRCA1, and schizophrenia and their nearest neighbors with which they tend to appear more frequently in biomedical literature, the similarity was more robust." (PMID 34653224, 2021). "Tissue-specific Brca1 knockout in breast progenitors leads to breast tumor formation." (PMID 33923105, 2021). "Moreover, BRCA1 is associated with transcription termination sites of highly transcribed genes that are enriched in genomic alterations in BRCA1-deficent breast tumors." (PMID 34359660, 2021). "A disease-specific microarray analysis of BRCA1-mutant breast tumor tissue over sporadic tumors expressing wild-type BRCA1 found that the expression of ESR1, which is a coding gene for ER alpha, was significantly lower in BRCA1-mutant tumor tissue than in sporadic tumor tissues." (PMID 35008774, 2021). "BRCA1-associated and basal-like breast tumours displayed greater transcriptome-wide variability compared to non-BRCA1 and non-basal-like (luminal A, luminal B, HER2 and normal-like) tumours." (PMID 34287743, 2021). "We find elevated levels of cells which resemble these hormone receptor negative luminal progenitor cells in breast tumour biopsies of hormone receptor negative cancers, as well as in healthy breast tissue samples from BRCA1 (FANCS) mutation carriers." (PMID 34880407, 2021). "Notably, we found that BRF2 amplification was mutually exclusive to the loss of BRCA1 and BRCA2 in breast tumors, both in the TCGA and METABRIC datasets." (PMID 34359683, 2021). "Breast Cancer 1 gene (BRCA1) is known to be inactivated in breast tumors by promoter methylation." (PMID 32175521, 2020). "Interestingly, ER/PR status of the first breast tumor was predictive of the ER/PR of the second cancer for both BRCA1 and BRCA2 carriers, suggesting that the second tumor arises in the same genetic and environmental background with the same pathology." (PMID 32481735, 2020). "The frequency of BRCA1 promoter methylation in non-BRCA mutated breast tumors is approximately 3% (29 out of 965; 3.0%)." (PMID 32175521, 2020). "As expected, CST cells are sensitive to cisplatin, a first-line platinum chemotherapy drug in BRCA1-mutated breast tumors, and to a panel of PARP inhibitors (olaparib, veliparib, rucaparib and talazoparib) designed to exploit the synthetic lethality of BRCA1-linked cancers." (PMID 32053991, 2020). "Moreover, hormone receptor status further stratified BRCA1/2 breast tumors with low-HRD TNBC tumors being more immunogenic than high-HRD HR+ tumors." (PMID 33718107, 2020). "Similar to BRCA1 deficiency, low expression of TRDMT1 in breast tumors may induce genomic instability but also render tumors responsive to radiotherapy." (PMID 32503981, 2020). "Thus, ADAT2 up-regulation observed upon BRCA1 inactivation in breast tumors exposes A34-to-I34 editing as a novel tRNA modification that is altered in cancer." (PMID 32290274, 2020). "Additionally, in a significant proportion of sporadic breast tumors, Breast Cancer 1 (BRCA1) promoter hypermethylation, transcription repression, or somatic BRCA1 pathogenic variants are responsible for its inactivation." (PMID 32290274, 2020). "Furthermore, 9 genes were associated with BRCA1-related breast tumours and 11 genes were associated with BRCA2-related breast tumours." (PMID 33081408, 2020). "BRCA1 is sometimes inactivated in breast tumors by promoter methylation." (PMID 32175521, 2020). "PI3K inhibition may render BRCA-proficient breast tumor cells more responsive to PARP inhibition through ERK signaling-mediated downregulation of BRCA1/2 expression." (PMID 32194423, 2020). "In agreement, there are data suggesting that theprevalence of loss of wild-type BRCA1 between ER+ and ER- invasiveBRCA1 breast tumors does not differ (Natrajanet al., 2012)." (PMID 31067289, 2019). "However, the comparison of BRCA1 mRNA expression between different subtypes of breast tumors is rarely available." (PMID 28646826, 2018).
breast tumors (continued). "The observations suggest that decreased BRCA1 expression, regardless of tumor subtype, has a general role in breast malignancy and associated with poor prognostic features in breast tumors." (PMID 28646826, 2018). "Nine miRNAs were identified, four that displayed increased expression (miR-34b-5p, miR-744-p, miR-485-3p, miR-542-3p) in both Brca1 knockout murine mammary glands and human BRCA1 breast tumours and five were decreased (miR-664-3p, miR-221-3p, miR-16-5p, miR-29b-1-5p and miR-30b-5p) in both datasets." (PMID 30323900, 2018). "As the expression of BRCA1 mRNA values for all four normal breast samples were between 0.51-2.38, values of ≥2.5 were considered as the overexpression t status and those of ≤0.4 as underexpression status in breast tumors." (PMID 28646826, 2018). "Interestingly, in our studied patients, BRCA1 overexpression was observed in two luminal tumors, which belonged to patients with older age at diagnosis (60 and 81 years) and low-grade breast tumors." (PMID 28646826, 2018). "The authors noticed that lack of BRCA1 in BRCA1-mutant breast tumors is associated with reduced expression of SIRT1 and high levels of survivin, and showed BRCA1 to positively regulate SIRT1 expression in vitro." (PMID 30380732, 2018). "BRCA1 expression was evaluated by real-time PCR in 26 triple-negative and 27 luminal breast tumors." (PMID 28646826, 2018). "Coherent with the failure of mutant BRCA1 to suppress IGF1R gene transcription, immunohistochemical analyses of primary breast tumors derived from a cohort of 185delAG BRCA1 mutation carrier patients revealed almost twofold higher IGF1R levels than in sporadic breast tumors." (PMID 28706506, 2017). "The FA pathway has also been connected to TNBC, as comparison of mRNA expression in different breast tumor types revealed several FA pathway genes (BRCA1, FANCD2, FANCF, and PALB2) being significantly less expressed in TNBC tumors compared to luminal A (ER or PR positive) tumors." (PMID 28702895, 2017). "Therefore, it would be interesting to examine BRCA1 Y1552 tyrosine phosphorylation on breast tumors." (PMID 29156836, 2017). "Additional ex vivo experiments using freshly isolated CSC-enriched cell populations from specific BRCA1 KO animals and primary breast tumor samples of distinct molecular subtypes should definitely clarify the role of the anti-RANKL antibody denosumab as a potential breast CSC-specific inhibitor." (PMID 28388533, 2017). "Moreover, high expression levels of DNMT3B and CTCF are critical in the epigenetic inactivation of BRCA1 in sporadic breast tumors." (PMID 28127428, 2017). "In addition to genetic mutations, our previous studies along with others have shown that the BRCA1 gene undergoes CpG promoter methylation in at least 5–10% of all sporadically arising breast tumors." (PMID 28679371, 2017). "Sporadic triple negative tumors share many characteristics with BRCA1-germline mutated breast tumors but they usually do not present somatic mutations in the BRCA1 gene." (PMID 26933805, 2016). "We have identified and cloned two major splice variants of BRCA1, namely BRCA1a/p110 and BRCA1b/p100, both are expressed at lower levels in ovarian and breast tumors as opposed to normal cells." (PMID 28164176, 2016). "The overexpression of this transcriptional repressor in breast tumors may be a relevant mechanism for BRCA1 silencing." (PMID 26979459, 2016).
breast tumors (continued). "Although the majority of breast tumors are sporadic and do not carry germline mutations in BRCA1 or BRCA2, it has been shown that the HR DNA repair pathway is frequently disrupted by numerous mechanisms." (PMID 27788678, 2016). "The incidence of BRCA1 methylation has previously been reported to be higher in breast tumors of infiltrating ductal type suggesting that it might play a role in breast carcinogenesis." (PMID 27413552, 2016). "However, BRCA1 male breast tumours trended toward higher grade compared with those in the general population (P for trend = 0.003)." (PMID 26857456, 2016). "Little is known about miRNA deregulation in hereditary breast tumors as no miRNA expression profiling studies have been performed in normal breast tissue of BRCA1 and BRCA2 mutation carriers." (PMID 26378051, 2015). "Gene expression profiling studies have disclosed specific molecular signatures for BRCA1/2-related breast tumors as compared to sporadic cases, which might help diagnosis and clinical follow-up." (PMID 26061043, 2015). "Finally, we examined the association between expression of AhR and BRCA-1 promoter CpG methylation in human triple-negative (TNBC), luminal-A (LUM-A), LUM-B, and epidermal growth factor receptor-2 (HER-2)-positive breast tumor samples." (PMID 26715507, 2015). "On the contrary, a reverse trend compared to microarray analysis was reported for miR-122 expression in familial breast tumors with and without BRCA1/2 mutations." (PMID 25333258, 2015). "Moreover, numerous studies demonstrated the methylation status of CpG islands in the promoter regions of BRCA1 gene was aberrant in patients with sporadic breast tumors compared with healthy females or patients with benign diseases." (PMID 26643130, 2015). "The microarray analysis revealed 16 miRNAs significantly differentially modulated (p<0.01) between BRCA1/2 carriers and breast tumors without BRCA1/2 mutations, as reported in the heatmap and in the volcano plot." (PMID 25333258, 2015). "Therefore, we compared the level of BRCA-1 promoter CpG methylation in genomic DNA obtained from control breast tissue and various breast tumor subtypes including TNBC, LUM-A, HER-2-positive, and LUM-B." (PMID 26715507, 2015). "Sporadic breast tumors do not harbor somatic mutations in BRCA-1 but express low or undetectable BRCA-1." (PMID 26715507, 2015). "BRCA1-mutated breast tumours are generally ER, PgR, and HER2/neu negative and poorly differentiated with a poor prognosis." (PMID 26061043, 2015). "Conversely, sporadic breast tumors, which represent 90-95 % of breast malignancies, have lower BRCA-1 expression, but not mutated BRCA-1 gene, and tend to occur later in life in combination with other genetic alterations and/or environmental exposures." (PMID 26715507, 2015). "Therefore, it is reasonably predicted that methylation of BRCA1 different promoter region and distinct region of BRCA1 gene play different role in the BRCA1 expression and prognosis in breast tumors, and this needs further study." (PMID 26643130, 2015). "BRCA1 nuclear staining was frequently reduced in breast tumor tissue compared to normal tissue." (PMID 25774336, 2015). "All three scores showed strong correlation with BRCA1/2 deficiency regardless of subtype, and the frequency of elevated scores suggests that a significant proportion of all breast tumor subtypes carry defects in the homologous recombination DNA repair pathway." (PMID 25475740, 2014). "Thus, BRCA1 expression is critical for mediating the biological impact of vitamin D3 in breast tumor cells." (PMID 25460500, 2014). "Gene expression was further tested in vivo by immunoflourescence staining on breast tumor tissue, comparing triple negative patient samples with the variant (TG or TT) or non-variant (GG) BRCA1 3’UTR." (PMID 24915755, 2014).
breast tumors (continued). "We report the genomic profiles for BRCA1-mutated, non-mutated and unscreened TN breast tumors using DNA arrays composed of 60,000 probes with an average resolution of 40 kb." (PMID 25416589, 2014). "We compared 41 basal breast tumors (27 BRCA1-mutated) and 79 not-basal breast tumors (8 BRCA1 mutated) for FA gene expression." (PMID 25161863, 2014). "For example, breast tumors from patients who are BRCA1/2 carriers have been shown to be heterogeneous, where not all cells have lost the second BRCA1/2 allele." (PMID 24639951, 2014). "Consistently, loss of wild-type BRCA1 is not the initiating step in tumorigenesis in BRCA-associated breast tumors." (PMID 25158060, 2014). "Moreover since BRCA1 tumors and sporadic triple negative (TN) breast tumors share similarities regarding clinical outcomes and some histological characteristics, we focused on TN and not TN cases." (PMID 25406994, 2014). "In addition, breast tumors arising in BRCA1 carriers have been shown to have increased expression of several stem cell markers." (PMID 24950059, 2014). "In addition, BRCA1-mutated breast tumor cells are more sensitive to oxidative stress than BRCA1-expressing cells This mechanism was correlated to the production of lipid droplets, which could further explain the increased total fatty acid content in BRCA1-mutated cells." (PMID 25010005, 2014). "Indeed, in 29% (14/48) of TN breast tumours BRCA1 promoter was hypermethylated compared to 5% (3/57) of HR-positive/HER2-negative and 2% (1/50) of HER2-positive tumours." (PMID 24191908, 2013). "Furthermore, HOXB13 and BRCA1 are all from “androgen-mediated pathway”, and are all found to be hypermethylated in breast tumors than normal tissues in our study." (PMID 23630576, 2013). "It seems that BRCA1 and BRCA2 gene mutations are associated with higher grades of breast tumors." (PMID 24312913, 2013). "In regarding to UV breast tumor samples, 3 (30%) and 7 (70%) out of 10 samples were clustered with BRCA1/2-associated and -negative tumors, respectively." (PMID 23469205, 2013). "A screen of non-BRCA1 or BRCA2 mutant familiar breast tumors identified a in-frame deletion of residue 81 glutamic acid of Rap80 that displays reduced ubiquitin binding and compromised ability to recruit A complex and BRCA1 to DSBs." (PMID 22369660, 2012). "Finally, breast tumor formation and progression in rats induced by the carcinogen, NMU was associated with induction in rat BRCA1-IRIS (mRNA) expression." (PMID 22511931, 2012). "To develop more efficient approaches to screening we have compared the gene expression and genomic profiles of BRCA2-mutant breast tumors with those of breast tumors lacking BRCA1 or BRCA2 mutations." (PMID 23284877, 2012). "We propose that BRCA1-IRIS inhibition may be pursued as a novel therapeutic option to treat these aggressive breast tumor subtypes." (PMID 22511931, 2012). "Immunohistochemical staining of large cohort of human breast tumor samples using new monoclonal anti-BRCA1-IRIS antibody, followed by correlation of BRCA1-IRIS expression with that of AKT1, AKT2, p-AKT, survivin and BRCA1/p220, tumor status and age at diagnosis." (PMID 22511931, 2012). "In this regard, it is noteworthy that ERBB2 amplification is absent in breast tumors from BRCA1 mutation carriers." (PMID 23181561, 2012). "Aberrant expression of a set of microRNAs have been found in breast tumor samples, and some of these microRNAs could target BRCA1 mRNA, thus possibly regulating BRCA1 expression." (PMID 21668996, 2011). "However, decreased BRCA1 expression is observed in sporadic breast tumours, with decreasing expression correlating with increasing tumour grade." (PMID 21609478, 2011). "83% of BRCA1 breast tumours were ER−, whereas 76% of BRCA2 breast tumours were ER+." (PMID 22312502, 2011). "Tumor characteristics of BRCA1-related, Luminal-J, basal-like and Luminal-H breast tumors." (PMID 21118481, 2010).
breast tumors (continued). "BRCA1-mutated breast tumors are associated with a specific aCGH profile which exhibits features that can be used to identify hereditary breast tumors for which information on BRCA1-mutation is not available." (PMID 21118481, 2010). "Numerous studies have linked the absence of oestrogen receptor (ER) expression in breast tumours with BRCA1 mutation carrier status using different laboratory methods, anti-ER antibodies, and cut-off points for ER staining." (PMID 20482762, 2010). "Furthermore, breast tumours in BRCA1/2 carriers are more likely to be bilateral and affect the contra lateral breast at a later stage." (PMID 20961453, 2010). "As regard to the clinical outcome of BRCA1/2-related breast tumors, several studies have been done in order to evaluate if germ-line cancer predisposing mutations might be useful for inclusion in different prognostic subgroups." (PMID 19825178, 2009). "The detailed information on the locations of genomic alterations provided by the high-resolution CGH arrays used here allowed us to more clearly delineate the distinct genetic pathways undertaken by breast tumours displaying either BRCA1 or BRCA2 abnormalities." (PMID 19589159, 2009). "It has been reported that CD44+/CD24−/low cells were more common in basal-like tumors and strongly associated with BRCA1 hereditary breast cancer; however, not every basal breast tumor contains CD44+/CD24−/low cells." (PMID 20027313, 2009). "In addition, cytoplasmic FIH appears as a prognostic marker in BRCA1 breast tumours conferring a shorter relapse-free and overall survival, despite its association with a lower grade, whereas no such differences are seen for nuclear FIH." (PMID 19724277, 2009). "All six breast tumours were unilateral; five were infiltrating ductal carcinomas, whereas the familial BRCA1/2 mutation-negative was of medullary type." (PMID 17242703, 2007). "Furthermore, BRCA1, PP1β and PP1γ were significantly higher in normal tissue specimens (BRCA1 p = 0.01, PP1β: p = 0.03, PP1γ, p = 1.9 × 10-6) compared to sporadic breast tumor samples." (PMID 17511879, 2007). "BRCA1 methylation was found in 13/143 (9.1%) sporadic breast tumours." (PMID 16846527, 2006). "BRCA1 methylation is frequent in primary sporadic breast tumours." (PMID 16846527, 2006). "Loss of the wild-type BRCA1 or BRCA2 allele has been shown in breast tumours arising in patients carrying a germline mutation in one of these genes and in some sporadic breast tumours." (PMID 16880780, 2006). "Thus, our results indicate phenotypic similarities between BRCA1 methylated and familial BRCA1 breast tumours." (PMID 16846527, 2006). "The present patient had an early onset breast tumor, but had both hereditary susceptibility due to her BRCA1 mutation and dense breasts, so her presentation is not unusual in this context." (PMID 15955237, 2005). "No sporadic breast tumours have been shown to harbour mutations in the coding sequence of BRCA1 or BRCA2." (PMID 12838319, 2003). "In conclusion, our findings support the hypothesis of a specific pattern of chemosensitivity in BRCA1 breast hereditary carcinomas when compared with breast tumours arising in the sporadic setting." (PMID 12698198, 2003). "While distinct tumour features can be used to estimate the likelihood that a breast tumour is caused by a BRCA1 germline mutation it is not yet possible to categorize a BRCA1 mutated tumour." (PMID 11506493, 2001).